BSN-DT (BSN divergent transcript)
Synonyms: BSN-AS2
Gene: Long non-coding RNA gene on chromosome 3 (49,534,453 to 49,554,374, reverse strand). Ensembl gene ENSG00000226913.
Diseases named in the same sentence as BSN-DT in open-access papers:
BSN-DT is named in the same sentence as 1 disease in open-access papers, as found by Europe PMC text mining. Sharing a sentence is not in itself a finding about the gene and the disease.
BSN-DT shares sentences with these, for which no sentence is quoted: cancer (1 paper).